PARP1 (poly(ADP-ribose) polymerase 1)
Diseases named in the same sentence as PARP1 in open-access papers (continued):
Sharing a sentence is not in itself a finding about the gene and the disease.
osteosarcoma (continued). "Overexpression of miR-124 reduced poly ADP-ribose polymerase 1 (PARP1) and ataxia telangiectasia mutated interactor (ATMIN) proteins expression in osteosarcoma cells, which reduced DNA repair capacity and increased sensitivity to DNA-damaging drugs, such as DOX." (PMID 28978183, 2017). "PARP1 is considered a potential target for overcoming chemotherapy resistance, as it enhances the repair of DNA-damaged cells by recruiting DNA damage response proteins, such as γH2AX and BRCA1/2, which are linked to reduced survival rates in osteosarcoma patients." (PMID 40283955, 2025). "Because the individual and combined expression patterns of PARP1, γH2AX, BRCA1, and BRCA2 were significantly associated with advanced clinicopathologic factors and survival of osteosarcoma patients, we evaluated the effects of PARP inhibition on the survival of osteosarcoma cells." (PMID 29784019, 2018). "Our results suggest that the expression of DDR molecules is useful for the selection of osteosarcoma patients that could potentially benefit from of anti-PARP1-γH2AX-BRCA1/2 therapy because these subgroups of osteosarcoma patients have a shorter survival rate even in low-stage osteosarcomas." (PMID 29784019, 2018). "A novel link between obesity and cisplatin resistance in osteosarcoma is established, highlighting the A1BG/NAMPT/PARP1 axis as a critical driver." (PMID 40560034, 2025). "To further evaluate the therapeutic potential of NAMPT and PARP1 inhibition in vivo, we employed a DIO model of osteosarcoma." (PMID 40560034, 2025). "To identify the PARP1-proximal proteome in human osteosarcoma (U2OS) cells, we fused full-length PARP1 to an engineered ascorbate peroxidase APEX2." (PMID 36350633, 2022). "By inhibiting both PARP1- and SIRT1-dependent cellular pathways, NMNAT1 inhibition can be a promising new tool in osteosarcoma chemotherapy." (PMID 34445574, 2021). "The role of PARP-1 in the anti-clonogenic effect is also supported by our unpublished data from experiments with PARP-1 and PARP-2 silenced osteosarcoma cells." (PMID 32392755, 2020). "Consistent with this, one study showed that osteosarcoma cell lines with BRCAness (MG-63, ZK-58, Saos-2, and MNNG-HOS) were sensitive to the PARP1 inhibitor talazoparib, while a cell line with a heterozygous BRCA2 mutation (U2-OS) was not." (PMID 32961800, 2020). "Individual knock-down of PARP1 significantly inhibited proliferation of U2OS, SaOS2, and MG63 osteosarcoma cells." (PMID 29784019, 2018). "Overexpression of miR-124 induced the DNA repair defect through binding to the 3′-UTR of the mRNAs of PARP1 and ATMIN, thus reversed drug resistance in osteosarcoma." (PMID 28978183, 2017). "Importantly, pharmacological inhibition of NAMPT and PARP1 using FK886 and Olaparib, respectively, reversed Adi‐CM‐induced cisplatin resistance and restored cisplatin sensitivity in osteosarcoma cells, DIO mouse models, and patient‐derived organoids." (PMID 40560034, 2025). "To test this, we assessed the expression of A1BG and DNA repair‐related proteins (PARP1, ATM, and p‐ATM) at various time points (0, 6, 12, and 24 h) following cisplatin treatment in osteosarcoma cells under A1BG‐depleted or recombinant A1BG‐supplemented conditions." (PMID 40560034, 2025). "This study reveals a novel mechanism by which obesity, through the abundant peritumoral adipocytes characteristic of tumors in obese individuals, promotes cisplatin resistance in osteosarcoma, highlighting the A1BG/NAMPT/PARP1 axis as a promising therapeutic target." (PMID 40560034, 2025). "Similar results are seen for RB-null SAOS2 osteosarcoma cells where dead/dying cells are not apparent in control populations but become prevalent after PARP1/2 trapping." (PMID 37704395, 2023). "Conversely, siRNA-mediated knockdown of PARP1 in osteosarcoma cells did not affect the abundance of total ERK142." (PMID 34725336, 2021).
osteosarcoma (continued). "Moreover, when we performed addition analysis on the combined expression patterns of PARP1, γH2AX, BRCA1, and BRCA2, 51% (18/35) of osteosarcomas were included in the poor-prognostic group." (PMID 29784019, 2018). "Therefore, this study evaluates the expression and prognostic significance of the individual and combined expression patterns of PARP1 and PARP1-related DDR molecules such as γH2AX, BRCA1, and BRCA2 in osteosarcomas." (PMID 29784019, 2018). "The expression of PARP1, γH2AX, BRCA1, and BRCA2 were grouped as positive in 74% (26 of 35 of cases), 57% (20 of 35 of cases), 49% (17 of 35 of cases), and 46% (16 of 35 of cases) of osteosarcomas, respectively." (PMID 29784019, 2018). "In conclusion, this study demonstrated that the individual and combined expression patterns of PARP1, γH2AX, BRCA1, and BRCA2 might be useful for the prediction of survival of osteosarcoma patients." (PMID 29784019, 2018). "Notably, an osteosarcoma cell line, U2OS, treated with ciclopirox did not demonstrate cleavage of PARP-1." (PMID 27557498, 2016).
small cell lung carcinoma (25 papers, 2016 to 2025). Small cell lung cancer (SCLC) is a highly aggressive malignant neoplasm, accounting for 10-15% of lung cancer cases, characterized byrapid growth, and early metastasis. "Another study showed that PARP1 is associated with longer progression-free survival in limited-stage small cell lung cancer among South Korean population." (PMID 33284833, 2020). "Both PARP-1 mRNA and protein are highly expressed in small cell lung cancer, but PARP-1 protein has been shown to associate with longer progression free survival (PFS) in limited-stage small cell lung cancer." (PMID 31877876, 2019). "Both PARP‐1 mRNA and protein are highly expressed in small cell lung cancer, but PARP‐1 protein has been shown to associate with longer PFS in limited‐stage small cell lung cancer." (PMID 30467127, 2018). "The nanoemulsion improved permeation followed by subsequent uptake by the PARP1-expressing small cell lung cancer (SCLC)." (PMID 34638660, 2021). "Poly (ADP-ribose) polymerase 1 (PARP1) is highly expressed in small cell lung cancer (SCLC) and has emerged as an attractive target for treatment of SCLC." (PMID 33134168, 2020). "Bioinformatic analysis indicated that poly ADP‐ribose polymerase 1 (PARP1) was a direct target of miR7‐5p, and PARP1 expression was inhibited by miR7‐5p in small cell lung cancer cells." (PMID 31823440, 2020). "Two studies have shown that PARP1 is highly expressed in small-cell lung cancer cell lines at the mRNA and protein levels in the USA, and SCLC cell lines was significantly more sensitive to PARP inhibitors than were NSCLC cell lines." (PMID 33284833, 2020). "Similar results have been shown in small cell lung cancer (SCLC) after the inhibition of either PARP1 or CHK1." (PMID 32283785, 2020). "Moreover, miR-335 was identified to regulate the chemo-radioresistance of small cell lung cancer cells by targeting PARP-1." (PMID 31147526, 2019). "HMGB1 also induces PARP1 self-modification, which promotes the interaction of PARP1 with LC3, which in turn triggers autophagy and, finally, chemotherapy resistance in small-cell lung cancer; therefore, HMGB1 may be a predictive biomarker of PARP1 response in small-cell lung cancer patients." (PMID 41296391, 2025).
asthma (22 papers, 2012 to 2025). "With regard to the pathogenesis of asthma, it was demonstrated that PARP-1 deficiency in OVA-induced allergic mouse models leads to a reduction of eosinophilia and Th2 cytokine production." (PMID 32509795, 2020). "In sensitized mice genetic ablation of PARP-1 or its enzymatic inhibition reduces inflammation and neutrophil infiltration, ameliorating allergic airway reactions, dyspnea and asthma-associated remodeling." (PMID 31877876, 2019). "In humans, a PARP-1 gene polymorphism (Val762Ala) was reported to be associated with a decreased risk of asthma, while PARP-1 activation is increased in PBMC and lung tissues from asthmatic patients." (PMID 31877876, 2019). "Contradictory reports are available in literature regarding the role of PARP-1 in asthma-associated airway remodeling." (PMID 28974953, 2017). "Different studies have been carried out by our research group to evaluate the role of PARP-1 in modulating asthma-associated cytokines production." (PMID 28974953, 2017). "In the last decade, significant research has been conducted to evaluate the role of PARP-1 in lung inflammation associated with asthma and ALI, using experimental models." (PMID 28974953, 2017). "Therefore, it would be of interest to investigate the levels of PARP-1 in eosinophilic and neutrophilic inflammation in asthma and associate this with miR-223 expression." (PMID 32509795, 2020). "We hope that positioning PARP-1 in context of lung inflammation associated with asthma, ALI, and COPD would provide better understanding and might enable us to develop new drugs in the area." (PMID 28974953, 2017). "A number of studies have shown that PARP-1 inhibition reduces the asthma-associated eosinophilia." (PMID 28974953, 2017). "Such increase in splenic Treg cell population might be an added protective trait in controlling asthma-associated inflammation by PARP-1 inhibition." (PMID 28974953, 2017). "Accordingly, it is reasonable to speculate that such PARP-1 polymorphism diminishes the susceptibility to asthma by reduction in catalytic activity of the enzyme." (PMID 28974953, 2017). "Interestingly, a PARP-1 polymorphism which decreases PARP-1 activity was associated with a decreased risk of asthma in a Turkish population." (PMID 24319363, 2013). "In asthma, excessive reactive oxygen and nitrogen species (ROS/RNS) production by inflammatory cells causes DNA damage and activates PARP1." (PMID 40634444, 2025). "Studies have shown that the expression and activity of PARP1 are increased in lung tissues from asthma mouse models and patients." (PMID 40634444, 2025). "The results showed that PARP1 and SDCBP had high diagnostic accuracy for asthma in the training set, with AUC values of 0.864 and 0.948, respectively." (PMID 40634444, 2025). "PARP1 is a pro-inflammatory master regulator and a driver of acute (LPS-induced) and chronic (asthma) lung inflammation, and its inhibition has been shown to ameliorate disease severity in conditions ranging from septic shock to hepatitis." (PMID 38071218, 2023). "The PARP-1 V762A polymorphism, which decreases enzymatic activity by 40% and is associated with reduced risk of asthma in humans ultimately exemplifies the relationship between PARP-1 and asthma." (PMID 36348405, 2022). "Previously, convincing evidence has highlighted that PARP-1 exerts a critical role in lung-related diseases, such as asthma, silicosis, and ARDS." (PMID 35190759, 2022). "We demonstrated that PARP-1 regulates the expression of many genes whose products are crucial in asthma by controlling NF-κB nuclear trafficking and the fate of STAT6 following IL-4 or allergen exposure." (PMID 36348405, 2022). "The role of PARP1 in immune-mediated inflammation, such as asthma and experimental allergic encephalopathy (a model of multiple sclerosis), also indicates the involvement of PARP1 in immunoregulation." (PMID 33923319, 2021).
asthma (continued). "Similar to NF-κB, PARP-1 activity is increased in asthma patients, which was measured in peripheral blood mononuclear cells and lung tissue compared to controls." (PMID 32509795, 2020). "Particularly, PARP-1 inhibition improves functional, biochemical, and morphometric parameters in an in vivo allergen-induced asthma-like reaction model and in a bleomycin-induced pulmonary fibrosis model." (PMID 31164820, 2019). "Our laboratory conducted a series of pioneering studies that revealed the critical role of PARP-1 in asthma pathogenesis." (PMID 31178661, 2019). "Based on the outcome of preclinical studies, we can safely say that PARP-1 inhibition is a beneficial strategy to block lung inflammation at least in asthma and ALI." (PMID 28974953, 2017). "Accordingly, it would be interesting to test the PARP-1 inhibitors (alone or in combination with steroids) in chronic respiratory disorders such as severe asthma and COPD with an aim to block recruitment of neutrophils into the airways." (PMID 28974953, 2017). "Overall, work conducted in past 14 years certainly place PARP-1 as a critical player in the orchestration of inflammatory response in asthma." (PMID 28974953, 2017). "Given the multifaceted role of PARP-1 in asthma, we have discussed its role in immune cells and structural cells along with the signaling mechanism influenced by the protein in the following section." (PMID 28974953, 2017). "Among the different members of the family, PARP-1 emerges as a key player in the orchestration of lung inflammation in asthma and ALI." (PMID 28974953, 2017). "STAT-6 and GATA-3 are reported to be central players in PARP-1-mediated eosinophilic inflammation in asthma." (PMID 28974953, 2017). "Recently, we have reported that PARP-1 inhibition blocks asthma-like traits in mice when exposed to house dust mite (HDM) which is an important human allergen." (PMID 28974953, 2017). "We also showed that PARP-1 regulates iNOS expression in an animal model of asthma and in cultured cells." (PMID 27524861, 2016). "Our laboratory pioneered the studies demonstrating the involvement of poly(ADP-ribose)polymerase (PARP)-1 in asthma." (PMID 26169874, 2015). "Overall, the results of the present study provide more support for the role of PARP-1 in asthma pathogenesis and the potential of PARP inhibition as a viable therapeutic strategy for the treatment of asthma in humans." (PMID 26169874, 2015). "In GSEA, PARP1 and SDCBP were associated with immune-related processes like ‘Antigen processing and presentation’ and ‘Adaptive immune response,’ emphasizing their role in immune regulation in asthma." (PMID 40634444, 2025). "The anoikis-related biomarkers PARP1 and SDCBP may serve as diagnostic markers and therapeutic targets for asthma." (PMID 40634444, 2025). "However, the exact mechanisms through which PARP1 influences anoikis and its role in asthma are yet to be fully understood." (PMID 40634444, 2025). "PARP2 deletion does not seem to influence Th2-mediated inflammatory processes, whereas the deletion or inhibition of PARP1 was anti-inflammatory in mouse models of contact hypersensitivity reaction, asthma, acute pancreatitis, allergic airway inflammation, and experimental colitis." (PMID 37351597, 2023). "Given the finding that phosphorylated STAT6 is the primary target for degradation upon PARP-1 inhibition, this represents a unique opportunity to target the transcription factor for degradation during asthma where the IL-4/IL-13/STAT6 pathway is upregulated especially in uncontrolled/severe disease." (PMID 36348405, 2022). "We reported that PARP-1 regulates genes whose products are crucial for asthma, in part, by controlling STAT6 integrity speculatively through a calpain-dependent mechanism." (PMID 36348405, 2022). "PARP-1 downregulation has been reported to suppress inflammation in a mouse model of asthma." (PMID 35190759, 2022).
asthma (continued). "A second important area that requires future research is the discrimination between different diseases phenotypes; e.g., eosinophilic, neutrophilic, paucigranulocytic asthma and the involvement of different target such as PARP-1 and NLRP3 in the determination of these phenotypes." (PMID 32509795, 2020). "PARP-1 also sustains Th2 type inflammation, in particular in allergic responses and asthma." (PMID 31877876, 2019). "In this study, we examined whether PARP-1 is critical for DC differentiation and function using bone marrow progenitors and their migration to the lung in an ovalbumin-based mouse model of asthma." (PMID 31178661, 2019). "Findings of the present study are important in clarifying not only the role of PARP-1 in asthma but also whether therapies that target PARP-1 affect DC differentiation and/or function in patients with cancer." (PMID 31178661, 2019). "Therefore, we reviewed the role PARP-1 in the context of asthma, ALI, and COPD with a special focus on inflammation." (PMID 28974953, 2017). "Therefore, we examined the effect of PARP-1 on IL-17 expression using experimental model(s) relevant to asthma." (PMID 28974953, 2017). "Studies on the role of poly(ADP-ribose)polymerase-1 (PARP-1) in asthma." (PMID 28974953, 2017). "However, it is yet to be explored whether such neutrophilic inflammation can be modulated by PARP-1 inhibition in severe asthma and/or COPD." (PMID 28974953, 2017). "Studies using knockout mice or soluble inhibitors (INO1001, 1,7-dimethylxanthine) found that PARP1 was essential in driving the development of lung injury in response to various noxious stimuli including mechanical ventilation, lipopolysaccharide induced sepsis, and allergen sensitization in asthma." (PMID 22520446, 2012). "Machine learning methods further narrowed down the six ARDEGs to two hub ARDEGs: PARP1 and SDCBP, which were significantly upregulated in asthma and validated using the GSE147878 and experimental models." (PMID 40634444, 2025). "Specifically, future experiments will explore the mechanisms underlying anoikis in asthma, and examine how the inhibition of PARP1 and SDCBP affects anoikis and airway inflammation in asthma mouse models." (PMID 40634444, 2025). "To further verify the expression levels of PARP1 and SDCBP, we performed RT-PCR and Western blot analysis on lung tissues from OVA-induced asthma mice, compared to control mice." (PMID 40634444, 2025). "This suggests that PARP1 helps balance CD4 T cell and T follicular helper cell functions, potentially influencing asthma modulation." (PMID 40634444, 2025). "Most cell types present in the lungs express abundant PARP-1 and PARP-2 in their nuclei and PARP inhibitors can modify their sensitivity to oxidative stress and possibly their role in asthma pathophysiology." (PMID 24444146, 2014). "Western blot and RT-PCR were used to further validate the expression of PARP1 and SDCBP in asthma." (PMID 40634444, 2025). "The results of molecular docking, qRT-PCR, and Western blot analysis suggest that PARP1, CDK2, and MAPK1 might play important roles in the treatment of asthma." (PMID 35399637, 2022). "The connection between PARP-1 and VCAM-1 provides an insight on how PARP-1 inhibition reduces asthma-like traits without affecting DC function." (PMID 31178661, 2019). "Since alternative medications are required in ALI and steroid non-responsive asthma, we next compile various studies addressing the role of PARP-1 in ALI with a focus on neutrophilic inflammation." (PMID 28974953, 2017). "Physiologically relevant levels of DNA damage and PARP-1 activation have been demonstrated in pulmonary diseases, such as asthma, acute lung injury, and COPD, however these have not been investigated in CF." (PMID 22988441, 2012).